SOX2 (SRY-box transcription factor 2)
Diseases named in the same sentence as SOX2 in open-access papers (continued):
Sharing a sentence is not in itself a finding about the gene and the disease.
melanoma (continued). "Importantly, SOX2 upregulation by FGF-1 promoted the survival of melanoma cells and significantly blocked ASA-induced reduced cell survival and increased apoptosis." (PMID 28636992, 2017). "Furthermore, our studies show that SOX-2 upregulation blocks FP receptor antagonist effects which mimics ASA-induced effects in inhibiting the survival of melanoma cells." (PMID 28636992, 2017). "We found that SOX2 is a potential target of miR-625 in malignant melanoma." (PMID 28129648, 2017). "We first tested if the same dosing regimen (10ng/ml) of FGF-1 at 24 hour could induce SOX2 in melanoma cells?" (PMID 28636992, 2017). "We checked the expression levels of SOX2 in malignant melanoma tissue and normal tissue." (PMID 28129648, 2017). "Furthermore, knockdown of SMO leads to a complete abolishment of SOX2 mRNA, suggesting that SOX2 is a downstream mediator of the Hh signaling pathway in melanoma CSCs." (PMID 26270676, 2015). "Indeed, ChIP sequencing in M26c melanoma CSCs demonstrated that SOX2 is a direct transcriptional target of GLI1 and GLI2." (PMID 26270676, 2015). "Melanoma cells maintained in the stem cell-like state showed a striking upregulation of a gene set related to development and neural stem cell biology, which included SRY-box 2 (SOX2) and Inhibitor of DNA Binding 4 (ID4)." (PMID 25642713, 2015). "As mentioned, SOX2 has also been detected in human melanoma." (PMID 25642713, 2015). "Furthermore, silencing of SOX2 in melanoma CSCs also decreased self-renewal in vitro and limited in vivo tumor initiation and growth of melanoma stem cells." (PMID 26053182, 2015). "The microarray results indicated that microenvironmental cues can trigger switching of melanoma cells to a neural stem cell-like pattern, as six genes related to neural stem cell and neural stem cell niche biology were upregulated: SOX2, ID4, GFRA2, S100A4, LGI4, and GJB1." (PMID 25642713, 2015). "Moreover, GLI1 and GLI2 downstream transcription factors of HH-GLI Signaling were able to bind to the proximal promoter of SOX2 in primary melanoma cells in chromatin immunoprecipitation (ChIP) studies and therefore SOX2 is regulated by HH signaling." (PMID 25114775, 2014). "Finally, specific examples of subclonality, such as MUC4 PMs in melanoma and SOX2 gains in lung, have been identified." (PMID 25160065, 2014). "We cannot exclude that other cell surface markers like ABCB5 or transcription factors like SOX2 may participate or even act as critical factors in the transition of melanoma cells phenotype." (PMID 24799129, 2014). "However, Sox2 is dispensable for primary melanoma growth and metastasis formation." (PMID 40754577, 2025). "Thus, it is suggested that studies involving the epithelial–mesenchymal transition pathways and invasion in oral canine melanomas may be related to increased SOX2 expression in this tumor type." (PMID 41012776, 2025). "Therefore, alantolactone combined MAPKi could dual suppress STAT3 and BRAF/MEK/ERK1/2 pathways, consequently inhibiting the expression of downstream Klf4, Oct4, Sox2 and c-Myc proteins, to enhance sensitivity of resistant melanoma to MAPKi." (PMID 38822350, 2024). "Specifically, Notch1-overexpressing CAFs were found to induce a sustained suppression of melanoma cell stemness; conversely, Notch1-silenced CAFs significantly increased the stemness properties of melanoma CSCs by upregulating the expression of the stemness markers Sox2, Oct4 and Nanog." (PMID 39199632, 2024). "Finally, sirtuin-1, zonula occludens-1, urokinase plasminogen activator surface receptor (uPAR) and SRY (sex determining region Y)-box 2 (SOX2) were also downregulated by ONC in A375 melanoma cells, in line with the low invasiveness and low metastatic potential effects previously found." (PMID 35742999, 2022).
melanoma (continued). "As SOX2 represents one of the key factors involved in melanoma stemness and tumorigenicity, we evaluated whether the role of SOX2 phosphorylation in limiting BRAFi sensitivity could be related to the induction of stem-like features, which are typically associated with drug resistance." (PMID 35944584, 2022). "Furthermore, functional studies show that SOX2 depletion increases sensitivity of melanoma cells to BRAFi, whereas overexpression of a phosphomimetic SOX2-S251E mutant is sufficient to drive resistance and desensitize melanoma cells to BRAFi in vitro and in a zebrafish xenograft model." (PMID 35944584, 2022). "We identified FMOD, an aberrantly produced and secreted ECM molecule and SOX2, a transcription factor involved in self-renewal, as likely players that might cooperate or regulate closely coordinated programs driving the outgrowth of melanoma brain metastasis." (PMID 35737114, 2022). "Furthermore, the SOX2/IFN-mediated tumor immune escape has also been demonstrated in melanoma." (PMID 35267473, 2022). "Furthermore, treatment with PLX4032 was more effective in reducing the clonogenic ability of SOX2-depleted melanoma cells (LV-shSOX2), whereas the clonogenic growth of SOX2 WT (LV-c) cells was only moderately affected by treatment with PLX4032 at the same doses." (PMID 35944584, 2022). "Therefore, we investigated the effects of SOX2 KD on melanoma cell viability and death." (PMID 33613844, 2021). "Therefore, SOX2 is an attractive therapeutic target for melanoma." (PMID 33613844, 2021). "Therefore, we examined the DUBs that regulate SOX2 in melanoma cells." (PMID 33613844, 2021). "Thus, understanding the mechanisms regulating the stability and degradation of SOX2 in melanoma especially by the ubiquitin-proteasome system might yield some strategies to target this oncogenic factor." (PMID 33613844, 2021). "Besides, SOX2 could predict a poor survival to ICIs in melanoma with PD-L1 high expression, thus providing a further mechanistic rationale for combining SAHA with ICIs." (PMID 33158915, 2020). "Importantly, SOX2 expression in melanoma is up-regulated by STAT3 activity." (PMID 32899370, 2020). "Therefore, we speculated crosstalk between CDK1 and SOX2/MYC in melanoma, and silenced SOX2 in human melanoma cells." (PMID 31080551, 2019). "However, the role of SOX2 in melanoma growth and progression is more controversial." (PMID 30466459, 2018). "Moreover, SOX2-positive melanoma cells tend to be more spindle-shaped and have more peripheral nestin pattern, which may represent a motile, more mesenchymal phenotype." (PMID 29455657, 2018). "Importantly, as SOX2 play crucial roles in tumor-resistance or anti-apoptotic responses to standard therapies, our studies indicate that anti-SOX2 targeting agent(s) could further be tested for melanoma chemoprevention." (PMID 28636992, 2017). "As the role of aspirin in modulating SOX2 expression in melanoma model wasnot been studied before, ours was the first report demonstrating the novel mechanismof action of aspirin in a highly aggressive murine melanoma model viaSOX2-dependent-PAF-R-independent pathway." (PMID 34927173, 2017). "Similarly, Sox2 IHC of 25 metastatic carcinoma and 10 metastatic melanomas in brain showed the same pattern, except that 16 and 2 cases of carcinoma and melanoma, respectively, had abundant Sox2-immunopositive tumor cells, consistent with previous literature (not shown)." (PMID 25713758, 2015). "Double-staining was performed with both Sox2 and a second tumor-specific marker (CD20 for NHL-CNS; CAM5.2 for carcinomas; HMB45 for melanoma) on the remaining 20 metastatic cases to determine whether the Sox2-immunopositive cells might be part of the neoplastic cell population." (PMID 25713758, 2015).
melanoma (continued). "The evidences showing that Sox2 expression was coincident with Aldh1a1 overactivation, and that Sox2 expression inhibited Aldh1a1 in AhR knockdown cells, suggest the existence of a coordinated pathway involving AhR-Aldh1a1-Sox2 in the regulation of stemness in melanoma cells." (PMID 26242870, 2015). "Five hub genes including CXCL11, ICAM1, LEF1, MITF, and STAT1 were identified, SUZ12, SOX2, TCF3, NANOG, and SMAD4 were determined as the most significant TFs in metastatic-melanoma." (PMID 39820173, 2025). "A study have highlighted, in melanoma nodal metastases, the existence of two distinct subpopulations of cells simultaneously expressing OCT4, SOX2, KLF4, and c-MYC markers—one located in the tumor nests and the other in the peritumoral stroma." (PMID 40806546, 2025). "Put differently, the conjunction of DHT and BRAF/MEK inhibitors can effectively block the pathways of STAT3/SOX2 and MAPK, decrease the growth and spread of drug-resistant primary melanoma cells, and promote apoptosis." (PMID 39944829, 2025). "In melanoma, CDK1 collaborates with Sox2 to promote tumor initiation, while in gastrointestinal stromal tumors, CDK1 emerges as a novel vulnerability independent of the cell cycle, offering potential therapeutic avenues for advanced-stage patients." (PMID 40746552, 2025). "In agreement with our findings in human melanoma, we found that aldh1a3 was the most enriched ALDH family isoform in the ALDHHigh cells, together with high tfap2b, sox2, and sox10, while melanoma cells with ALDHLow activity expressed irf1b." (PMID 38963759, 2024). "Module M3 contained JUND, SOX2, THAP11, and JUN, as well as regulators for C5 Melanoma MAGEA4, C6 Melanoma GJB2, C2 melanoma EDNRB, and C1 melanoma CDH19." (PMID 37435067, 2023). "Of note, nests of stem-like melanoma cells have been identified in metastatic lesions in head and neck cancer patients and shown to express NANOG, OCT4, SOX2, KLF4, and cMYC." (PMID 37270599, 2023). "We propose the p38-dependent regulation of SOX2 phosphorylation and activity as a mechanism of adaptive response toward BRAF-targeted therapy in melanoma cells." (PMID 35944584, 2022). "In agreement with that, ectopic SOX2 decreased melanoma cell sensitivity to PLX4032, although this effect appeared stronger in cells expressing low levels of SOX2 (SK-MEL-5) compared to cells expressing high levels of SOX2 (A375 and A2058)." (PMID 35944584, 2022). "HERV-K expression is considerably higher in malignant tissues such as germ cell tumors, melanomas, and ovarian cancers than in healthy tissues (49, –, 52), suggesting that the transactivation of HERV-K LTR5Hs by SOX2 is involved in numerous malignant tumors." (PMID 35420440, 2022). "Protein coimmunoprecipitation of SOX2 and p38 in absence or presence of PLX4032 revealed that SOX2 and p38 proteins directly interact in A375 melanoma cells." (PMID 35944584, 2022). "We recently showed the critical role of SOX2 in promoting an undifferentiated, CSC-like phenotype in melanoma, and in regulating tumorigenicity of these CSCs." (PMID 35944584, 2022). "Phosphorylation of human SOX2 by CDK1 at S249-S250-S251 enhances its nuclear localization and transcriptional activity in melanoma cells." (PMID 35944584, 2022). "Melanoma Stem Cells (OL-SCs) were isolated and purified from OL cells, spherical in shape, grown in suspension, and expressed Aldh1, CD133, Nanog, Oct4 and Sox2 stemness markers." (PMID 36182945, 2022). "Kruppel-like factor 4 (KLF4) and sex-determining region Y-box 2 (SOX2) have been reported as essential transcription factors that maintain CSC stemness and invasion activity in melanomas, in addition to many other cancer cells." (PMID 34106558, 2021). "In support of the biological relevance of the transcriptional regulation of GLI1 by SOX2, we found a statistically significant correlation between SOX2 and GLI1 expression in a panel of metastatic melanoma cells (Pearson score R = 0.664, p = 0.036)." (PMID 33958721, 2021).
melanoma (continued). "Human primary melanoma tumor explants (established in NSG mice) show that both Usp9x DUB activity and SOX2 expression are elevated in metastatic tumors when compared to those with inefficient metastatic activity." (PMID 33613844, 2021). "Furthermore, comparison of GLI1 and SOX2 expression levels in 477 TCGA melanoma patients showed a co-expression of these two transcripts (p < 0.0001) and a significant decrease in overall survival in cases with high expression of both SOX2 and GLI1 (p = 0.0213)." (PMID 33958721, 2021). "We examined Usp9x and SOX2 expression levels in a panel of BRAF- and NRAS-mutant melanoma cell lines." (PMID 33613844, 2021). "Usp9x knockdown, as well as inhibition with DUB inhibitor, G9, blocked SOX2 expression, suppressed in vitro colony growth, and induced apoptosis of BRAF-mutant melanoma cells." (PMID 33613844, 2021). "Consistently, authors demonstrated that ST3GAL1 mediates SOX2- and GLI1-induced melanoma invasiveness." (PMID 33921986, 2021). "Recently, a reciprocal regulation between SOX2 and GLI1 has been described to fuel aberrant glycosylation/sialylation during melanoma progression." (PMID 33958721, 2021). "SOX2 induction (mRNA and protein) was observed by mutant BRAF inhibitor vemurafenib treatment in melanoma." (PMID 33613844, 2021). "Vemurafenib and MEKi treatment induced SOX2 in a time-dependent manner in both BRAF- and NRAS-mutant melanoma." (PMID 33613844, 2021). "Depletion of SOX2 using two independent shRNAs significantly decreased the expression of GLI1 mRNA and protein in several melanoma cell types." (PMID 33958721, 2021). "We showed that similar to Usp9x KD, G9 treatment also decreased SOX2 levels in BRAF-mutant melanoma cells and MG132 treatment reversed the reduction of SOX2 by G9." (PMID 33613844, 2021). "Since BRD4 is highly expressed in melanoma, we investigated its requirement in the binding and transactivation of GLI1 promoter by SOX2." (PMID 33958721, 2021). "Overall, SOX2 plays a key role in inhibiting HIF1A and inducing oxidative phosphorylation and enabling melanoma cells to shift metabolism in response to an acidic microenvironment." (PMID 34831420, 2021). "The western blot also elucidated that ST3GAL1, SOX2, GLI1, and AXL all have higher expression in metastatic melanomas as compared to primary melanomas." (PMID 35008286, 2021). "Although stemness features have been attributed to melanoma, our evaluation of stemness genes (NANOG, POU5F1, PROM1 and SOX2), revealed a very low expression among the tested cells on 2D culture." (PMID 32230715, 2020). "To further support the relevance of the SOX2/GLI1-ST3GAL1-AXL axis in melanoma progression, we performed single-cell analysis in cells derived from melanoma brain metastasis PDX models (M12, M15, and M27) as well as normal melanocyte cultures." (PMID 33203881, 2020). "Our results showed that SOX2 low expression conferred significant improvement in OS and PFS, and was an independent predictor of OS in melanoma with PD-L1 high expression." (PMID 33158915, 2020). "This is in agreement with previous studies showing that SOX2 and GLI1 are both involved in melanoma progression." (PMID 33203881, 2020). "Here we show the induction of the self-renewal and pluripotency markers Nanog, KLF4, OCT4, and SOX2 and the over-expression of the CSC markers CD133, CD243, and ALDH1A1 in melanoma cells exposed to chronic acidosis compared with control cells." (PMID 32803272, 2020). "In support of this regulation, a positive correlation between the expression of SOX2 and ST3GAL1 mRNA was observed in a panel of commercial and patient-derived melanoma cells." (PMID 33203881, 2020). "Transplantation under the mouse kidney capsule diminished SOX2+ neuronal precursors and PMEL+ melanoma cells." (PMID 31784515, 2019).
melanoma (continued). "In addition, we already know that melanoma cell exposure to extracellular acidosis deeply inhibits HIF1α expression, leaving tumor cells to acquire an OxPhos phenotype, probably under the influence of the increased SOX2 expression, and able to maximize energy efficiency with the available resources." (PMID 30466459, 2018). "We show for the first time that phenformin reduces stem cell features in melanoma by downregulating ALDH and SOX2 expression levels." (PMID 28036292, 2017). "We have previously shown that ALDHhigh cells in melanoma retain a CSC phenotype and recently, a role for SOX2 in sustaining the tumorigenic ability of ALDHhigh melanoma cells has been demonstrated." (PMID 28036292, 2017). "As expected, ALDHhigh melanoma cells express significantly higher levels of ALDH1A3, SOX2 and CD271 than ALDHlow cells by real time PCR, western blotting (SOX2/ALDH1A1) and FACS analysis (CD271)." (PMID 28036292, 2017). "Our studies demonstrate that ASA treatment inhibits SOX2 gene expression and modulation of SOX2 by PGF2α attenuates ASA-induced inhibition of survival and induction of apoptosis in murine B16F10 melanoma cells." (PMID 28636992, 2017). "As ASA-induced effects were blocked by modulation of SOX2 by PGF2α and FGF-1 in melanoma cells, we next investigated if PGF2α-FP receptor antagonist, AL8810 can mimic ASA effects and if SOX-2 upregulation can abrogate its effect?" (PMID 28636992, 2017). "Here, we report successful generation of human iPSCs from terminally differentiated melanoma TILs that express high levels of PD-1 by Sendai virus- (SeV-) mediated transduction of the four transcription factors OCT3/4, SOX2, KLF4, and c-MYC." (PMID 27057178, 2016). "In primary melanoma cells, GLI1 and GLI2 have been reported to bind the proximal SOX2 promoter, indicating that SOX2 is regulated, in part, by Hedghog-GLI signaling." (PMID 27225481, 2016). "Here, we describe the derivation of human iPSCs from melanoma TILs expressing high level of PD-1 by Sendai virus-mediated transduction of the four transcription factors, OCT3/4, SOX2, KLF4, and c-MYC." (PMID 27057178, 2016). "Among these genes MITF, WNT/beta Catenin, SOX9, SOX2, PAX3, RANK/RANKL are important in melanocyte differentiation and melanoma." (PMID 25612317, 2015). "For example, Nanog (fold = 13.3, q < 0.0005), Oct4 (fold = 3.8, q < 0.0005), Sox2 (fold = 1.5, q = 0.018) and LIN28 (fold = 2.3, q = 0.033) were all significantly downregulated in primary malignant melanoma samples compared to normal skin samples (GDS1375)." (PMID 19094235, 2008). "Interestingly, four genes known to be related to cancer cell stemness in malignant melanoma (ALDH1A3, BSG, NGFR, SOX2) were expressed at significantly high levels in CTCs with a high “platelet signature” (p = 0.0204, 0.0012, 0.0183, 0.0200, respectively)." (PMID 40003901, 2025). "Sox2, CD24 and ALDH regulate self-renewal, sphere formation and tumorigenicity of melanoma CSCs." (PMID 40754577, 2025). "Although the expression of SOX2 is quite controversial, and the role of the SOX3 protein has not yet been elucidated, the SOX10 protein, another member of this family of transcription factors, has already been widely studied in melanomas." (PMID 41012776, 2025). "Due to its relationship with aggressiveness in different tumor types, we hypothesized that proteins SOX2, SOX3 and SOX10, in canine melanomas, play a role similar to that observed in human neoplasms." (PMID 41012776, 2025). "In BRAF mutant melanoma cells, DHT suppresses the STAT3/SOX2 signaling pathway." (PMID 39944829, 2025). "Besides p300, in melanoma, SOX2 forms a complex with GLI1 and cooperatively transactivates ST3GAL1, which promotes melanoma metastasis via upregulating AXL." (PMID 38331879, 2024). "In melanoma cells, SOX2 activates GLI1 in a non-canonical SMO-independent way by binding to the CTTGGATT sequence at -423 bp upstream of the TSS and activating GLI1 expression." (PMID 37149646, 2023).